LRP8 (LDL receptor related protein 8)
Description:
Cell surface receptor for Reelin (RELN) and apolipoprotein E (apoE)-containing ligands. LRP8 participates in transmitting the extracellular Reelin signal to intracellular signaling processes, by binding to DAB1 on its cytoplasmic tail (By similarity). Reelin acts via both the VLDL receptor (VLDLR) and LRP8 to regulate DAB1 tyrosine phosphorylation and microtubule function in neurons (By similarity). LRP8 has higher affinity for Reelin than VLDLR (By similarity). LRP8 is thus a key component of the Reelin pathway which governs neuronal layering of the forebrain during embryonic brain development (By similarity). Binds the endoplasmic reticulum resident receptor-associated protein (RAP) (By similarity). Binds dimers of beta 2-glycoprotein I and may be involved in the suppression of platelet aggregation in the vasculature. Highly expressed in the initial segment of the epididymis, where it affects the functional expression of clusterin and phospholipid hydroperoxide glutathione peroxidase (PHGPx), two proteins required for sperm maturation (By similarity). May also function as an endocytic receptor (By similarity). Not required for endocytic uptake of SEPP1 in the kidney which is mediated by LRP2 (By similarity). Together with its ligand, apolipoprotein E (apoE), may indirectly play a role in the suppression of the innate immune response by controlling the survival of myeloid-derived suppressor cells (By similarity). (Microbial infection) Acts as a receptor for Semliki Forest virus. (Microbial infection) Acts as a receptor for tick-borne encephalitis virus by mediating viral cell attachment and internalization.
Synonyms: LRP-8; APOER2; MCI1; HSZ75190
Tractability: Antibody: UniProt places it where antibodies can reach, with high confidence; its Gene Ontology location is reachable by antibodies, with high confidence; UniProt predicts a signal peptide or a membrane-spanning region. PROTAC: UniProt records ubiquitination sites on it; ubiquitination databases record sites on it; its protein half-life has been measured.
Gene: Protein-coding gene on chromosome 1 (53,242,364 to 53,328,469, reverse strand). Ensembl gene ENSG00000157193.
Subcellular location: Cell membrane; Secreted
Pathways (Reactome):
Hemostasis: Platelet sensitization by LDL
Sensory Perception: Retinoid metabolism and transport
Gene Ontology:
Molecular function: protein binding; very-low-density lipoprotein particle receptor activity; apolipoprotein binding; cargo receptor activity; low-density lipoprotein particle receptor activity; reelin receptor activity; transmembrane signaling receptor activity; calcium ion binding; high-density lipoprotein particle binding; kinesin binding
Biological process: endocytosis; ammon gyrus development; cytokine-mediated signaling pathway; lipid metabolic process; modulation of chemical synaptic transmission; positive regulation of dendrite development; positive regulation of dendritic spine morphogenesis; proteolysis; reelin-mediated signaling pathway; regulation of apoptotic process; regulation of innate immune response; retinoid metabolic process; signal transduction; ventral spinal cord development; cellular response to cholesterol; cellular response to growth factor stimulus; cerebral cortex development; response to xenobiotic stimulus
Cellular component: caveola; membrane; plasma membrane; receptor complex; extracellular region; axon; dendrite; microtubule associated complex; neuronal cell body
Genetic constraint (gnomAD): Loss-of-function variants: 41 observed, 101.49 expected, observed/expected ratio (o/e) 0.4, 90% interval 0.31 to 0.52. The upper end of that interval is the gene's LOEUF score, 0.52, which puts it in group 2 of 6, group 1 being the genes least tolerant of losing a copy. Missense variants: 897 observed, 1,164.7 expected, observed/expected ratio (o/e) 0.77, 90% interval 0.73 to 0.81. Synonymous variants: 427 observed, 444.65 expected, observed/expected ratio (o/e) 0.96, 90% interval 0.89 to 1.04.
Homologues: Orthologues: chimpanzee LRP8 (99% identical), macaque LRP8 (97% identical), pig LRP8 (91% identical), mouse Lrp8 (90% identical), rat Lrp8 (89% identical), dog LRP8 (83% identical), rabbit LRP8 (82% identical), guinea pig LRP8 (77% identical), tropical clawed frog lrp8 (61% identical), zebrafish lrp8 (55% identical), Drosophila melanogaster arr (16% identical). Paralogues in human: VLDLR (44% identical), LRP1B (34% identical), LRP1 (33% identical), LRP2 (31% identical), LRP4 (26% identical), LRP5 (20% identical), LRP6 (20% identical), EGF (20% identical), NID1 (18% identical), NID2 (17% identical), LRP12 (14% identical), and 2 more.
Diseases named in the same sentence as LRP8 in open-access papers:
LRP8 is named in the same sentence as 110 diseases in open-access papers, as found by Europe PMC text mining. Sharing a sentence is not in itself a finding about the gene and the disease. The quoted sentences say what the papers report.
Alzheimer disease (25 papers, 2011 to 2026). A progressive, neurodegenerative disease characterized by loss of function and death of nerve cells in several areas of the brain leading to loss of cognitive function such as memory and language. "Recently, liver-X nuclear receptor (LXR) activation by agonism RGX-104 has been shown to enhance the transcription of ApoE (genetic risk factor for Alzheimer’s disease), which combines with low density lipoprotein receptor-related protein 8 (LRP8) and induces the depletion of MDSCs." (PMID 32325683, 2020). "Previous study has reported that LRP8 might have been associated with Alzheimer's disease when LRP8 gene polymorphism occurred." (PMID 31031810, 2019). "LRP8 has long been studied for its role in cholesterol transport and metabolism; however, the identification of ApoE4, the major genetic risk factor for developing late-onset Alzheimer’s disease, as one of its ligands has brought attention to its role in CNS-related pathways and neurodegeneration." (PMID 36012187, 2022). "Evidence for this protein’s involvement in neurological disorders is largely related to its role in Alzheimer’s disease, including supportive evidence of higher levels of LRP8 in Alzheimer’s disease cases vs. controls." (PMID 38397929, 2024). "Regarding LRP8, it is not known if its processing by γ-secretase is altered in patients with Alzheimer’s disease, and the consequences of this processing on amyloid formation are still underexplored." (PMID 36012187, 2022).
lung carcinoma (15 papers, 2012 to 2025). "LRP8 is associated with the occurrence and development of various cancers, including lung cancer, breast cancer, pancreatic cancer, prostate cancer, and hepatocellular carcinoma." (PMID 38544827, 2024). "This suggests that lung cancer CAFs also have a collagen gene response through SPON1/LRP8 signaling, but cancer cells are also capable of “mimicking” CAFs by using the SPON1/LRP8 axis to produce collagen." (PMID 38716730, 2024). "LRP8 is overexpressed in various cancers, including osteosarcoma and lung cancer, and its overexpression is significantly correlated with adverse clinical pathological features and prognosis." (PMID 38544827, 2024). "In particular, LRP8 level was markedly increased in lung cancer tissues compared with the control group, apparently acting as an oncogene." (PMID 36012187, 2022). "We used online bioinformatics databases to identify the expression of LRP8 in multiple types of lung cancer." (PMID 35246020, 2022). "Among the 363 up-regulated genes, 32 are prognostic markers in lung cancer, all of unfavorable prognosis, including LRP8, NUP62CL, FSCN1, PLCD3 or HMGA1." (PMID 36544755, 2022). "It was discovered that miR-30b-5p-targeted LRP8 re-sensitizes lung cancer cells to DDP, acting as a tumor suppressor." (PMID 36232582, 2022). "Low‐density lipoprotein receptor‐related protein 8 (LRP8) has been widely studied in cancer, and related research has evidenced that highly expressed LRP8 can facilitate the development of lung cancer (LC), BC, prostate cancer, gastric cancer (GC), and melanoma." (PMID 40372166, 2025). "In addition, miR-30b-5p inhibits lung cancer cell viability, migration and invasion and enhances cell sensitivity to cysplatin via targeting LRP8, suggesting that miR-30b-5p inhibits lung cancer progression by targeting LRP8." (PMID 36012187, 2022). "In addition, the miR-30b-5p inhibits lung cancer progression and enhances cisplatin sensitivity by targeting LRP8." (PMID 34819077, 2021). "LRP8 (8-fold) is overexpressed in lung cancer and involved in lung tumorigenesis." (PMID 22905093, 2012). "Additionally, miR-30b-5p has been shown to reduce the viability, migration, and invasion of lung cancer cells by targeting LRP8, suggesting that miR-30b-5p may inhibit lung cancer progression through LRP8 modulation." (PMID 40506610, 2025). "Low-density lipoprotein receptor-related protein 8 (LRP8) is involved in the development of multiple tumors, including lung cancer." (PMID 35246020, 2022). "In addition, the specific roles of novel NRF2-targeted genes such as ABHD14B, LRP8, and SLC27A5 in lung cancer need to be investigated." (PMID 29050246, 2017).
breast carcinoma (13 papers, 2013 to 2025). "The poor prognosis of breast cancer patients has been associated with the upregulation of LRP8 and negatively correlated with miR-1262 overexpression." (PMID 36791156, 2023). "Abnormal LRP8 expression has also been associated with breast cancer progression, where it facilitates cell growth and confers a poor prognosis in patients." (PMID 36012187, 2022). "Functionally, deletion of LRP8 in breast cancer cells impairs cell proliferation, clone formation, invasion, and migration abilities, consistent with an upregulated miR-1262 effect." (PMID 36791156, 2023). "Further, LRP8 depletion reduces breast cancer stem cells and inhibits EMT by regulating the Wnt/β-catenin signaling pathway in triple-negative breast cancer." (PMID 35246020, 2022). "Overall, these results demonstrate that LRP8 is essential for breast cancer cell survival and that its depletion impairs tumorigenic properties of the tested cells." (PMID 30575334, 2019). "We knocked down LRP8 expression with two different siRNAs against LRP8 (#2 and #3) in the panel of 13 breast cancer cell lines." (PMID 30575334, 2019). "LRP8 expression in breast cancer cell lines was similar to that in biopsy specimens, with the highest levels observed in cell lines without ER expression, in contrast to the study of Arun et al21 reporting no differential expression by ER status." (PMID 30575334, 2019). "The objective of our study was to determine the levels of LRP8 in all major subtypes of breast cancers using patient samples and a large panel of breast cancer cell lines." (PMID 30575334, 2019). "Furthermore, we identified the Reelin-LRP8 signaling pathway as a key regulatory mechanism in aggressive brain metastatic breast cancer, with LRP8 enhancing CDC42 activation to promote filopodia formation, dependent on Reelin." (PMID 40506610, 2025). "Therefore, miR-1262-regulated LRP8 can regulate cell proliferation and migration and other processes to promote breast cancer development." (PMID 36791156, 2023). "Moreover, inhibition of LRP8 was found to attenuate Wnt/β-catenin signalling to suppress breast cancer stem cells (BCSCs) enriched in TNBC and responsible for chemoresistance and metastasis." (PMID 35167614, 2022). "We first evaluated LRP8 protein levels in a panel of 13 breast cancer cell lines." (PMID 30575334, 2019). "We found LRP8 as one of the overexpressed genes in TNBC and also one of the top hits from our siRNA screen across 18 breast cancer cell lines, showing significant and preferential growth inhibition in TNBC cell lines (data not shown)." (PMID 31624295, 2019). "LRP8 depletion decreased cell proliferation more efficiently in estrogen receptor‐negative breast cancer cell lines: TNBC and HER2 overexpressing cell lines." (PMID 30575334, 2019). "By analyzing 13 breast cancer cell lines, we found that TNBC and ER−/HER2+ cell lines were more sensitive to LRP8 depletion than cell lines expressing ER However, analysis of additional ER+ cell lines should be performed in order to further substantiate this statement." (PMID 30575334, 2019). "Although a previous report showed that LRP8 expression was higher in ER−/HER2− (our TNBC group) compared to ER+/HER2− (our LA group) tumors, a complete analysis of all breast cancer subtypes allows us to consider LRP8 as a relevant therapeutic target for both ER−/HER2+ and TNBC subtypes." (PMID 30575334, 2019). "We found that LRP8 was more strongly expressed (at the mRNA level) in breast cancers without hormone receptor expression (TNBC [ER−/PR−/HER2−], ER−/HER2+) than in luminal tumors (luminal A [ER+/HER2−], luminal B [ER+/HER2+]), and normal breast tissues." (PMID 30575334, 2019).
breast carcinoma (continued). "With the exception of UQCRH and LRP8, the expression levels of genes positively correlated with YBX1, such as CTPS1, FMNL2, CDC20, B3GNT5, MTHFD1L, and CDCA8, were significantly and positively correlated with the expression level of YBX1 in 13 breast cancer cell lines." (PMID 30647855, 2018). "Using two different siRNAs, we showed that LRP8 depletion impaired more strongly the proliferation of estrogen receptor‐negative (TNBC and ER−/HER2+) breast cancer cell lines compared to the luminal cell lines." (PMID 30575334, 2019).
myocardial infarction (11 papers, 2009 to 2025). Gross necrosis of the myocardium, as a result of interruption of the blood supply to the area, as in coronary thrombosis. "Common polymorphisms in the LRP8 gene are associated with coronary artery disease, myocardial infarction, and high birth weight." (PMID 28396702, 2017). "LRP8 gene has been associated with triglyceride levels, coronary artery disease, and myocardial infarction." (PMID 28002425, 2016). "Genetic variation in the LRP8 gene in humans was shown to influence myocardial infarction and the early onset of coronary artery disease." (PMID 34321020, 2021). "The R952Q variant in the low density lipoprotein receptor-related protein 8 (LRP8)/apolipoprotein E receptor 2 (ApoER2) gene has been recently associated with familial and premature myocardial infarction (MI) by means of genome-wide linkage scan/association studies." (PMID 19439088, 2009). "We further uncovered associations between the regions of lobule VII and exonic variants of LRP8 and ABCG2, both genes being implicated in familial and premature coronary artery disease and myocardial infarction, and cardiovascular disease risk factors, respectively." (PMID 34853362, 2021). "Low-density lipoprotein receptor-related protein 8 (LRP8) or apolipoprotein E receptor 2 (ApoER2) is a member of the low density lipoprotein receptor family and is implicated in premature coronary disease, as well as myocardial infarction." (PMID 32664652, 2020). "The low density lipoprotein receptor-related protein 8 (LRP8) gene, located on chromosome 1p34-36, is an example of successful use of this type of approach in discovering genes for coronary artery disease (CAD) and myocardial infarction (MI)." (PMID 19439088, 2009).
schizophrenia (11 papers, 2016 to 2024). A major psychotic disorder characterized by abnormalities in the perception or expression of reality. "Pik3ca also interacts with Lrp8, a gene related to the onset of neuropsychiatric diseases, such as schizophrenia, Mapk8, a gene associated with reduced apoptosis in glioblastoma cells, and Sorl1, which is decreased in AD brains by regulating Aβ accumulation." (PMID 36614117, 2022). "The LRP8 was considered a susceptibility gene for schizophrenia and bipolar disorder." (PMID 34659328, 2021). "Concordant directions of effect were observed between plasma- and CSF-derived relative LRP8 abundance, with higher LRP8 associated with lower fluid intelligence scores and odds of physical activity, as well as a reduced liability to BPD and schizophrenia." (PMID 38397929, 2024). "LRP8 is a component of the NMDA receptor complex (NMDA-R), which has repeatedly implicated in schizophrenia." (PMID 31691811, 2020). "In addition, higher cortical expression of LRP8, but lower relative abundance in the CSF and plasma was related to higher odds of engaging in physical activity and a higher liability to schizophrenia (LRP8CSF and LRP8cortex only) and BPD." (PMID 38397929, 2024). "Genetically predicted low-density lipoprotein receptor-related protein 8 (LRP8) abundance in the CSF had the second-broadest effect through its association with lower fluid intelligence scores, reduced odds of physical activity as well as a reduced liability to BPD and schizophrenia." (PMID 38397929, 2024). "It should be noted that LRP8 has non-synaptic functions of credible relevance to schizophrenia, including mediating reelin-related functions on neuronal migration, neurogenesis and neuronal differentiation." (PMID 31691811, 2020).
atherosclerosis (10 papers, 2015 to 2025). A disease characterized by the build-up of fatty material and calcium deposition in the arterial wall resulting in partial or complete occlusion of the arterial lumen. "The Lrp8WTLdlr−/−, Lrp8+exon19Ldlr−/− and Lrp8Δexon19Ldlr−/− mice were fed a Western-type high-fat–high-cholesterol diet for 16 weeks prior to atherosclerosis assessment." (PMID 40722764, 2025). "Apolipoprotein E receptor-2 (apoER2), the protein encoded by the LRP8 (LDL receptor-related protein-8) gene, is present in the cells involved in atherosclerosis pathogenesis such as platelets, endothelial cells, and monocytes/macrophages." (PMID 40002707, 2025).
selenium deficiency (8 papers, 2016 to 2024). A nutritional deficiency disease resulting from inadequate selenium levels in the body, which can lead to impaired function of selenoproteins essential for antioxidant defense and thyroid hormone metabolism. "A crucial component of the intracellular selenium transportation system, the LRP8/ApoER2 complex is increased in chronic selenium deficiency, suggesting this process as important feedback to avoid chronically low SELENOP levels." (PMID 35056706, 2022). "In selenium deficiency, the “alphabet” selenoproteins are affected hierarchically, both with respect to the particular selenoprotein and the tissue of expression, as the brain or endocrine glands are hardly affected by Se deficiency due to their equipment with LRP2 or LRP8." (PMID 37958974, 2023). "PS mutations commonly impair Notch processing, with some exceptions, but can also impair the trafficking of LRP8, which could also induce selenium deficiency in the absence of a Notch deficit." (PMID 35449212, 2022).